APOE (apolipoprotein E)
Diseases named in the same sentence as APOE in open-access papers (continued):
Sharing a sentence is not in itself a finding about the gene and the disease.
atherosclerosis (continued). "Cardiovascular disease assessed by atherosclerosis and aortic calcification was not exacerbated by the presence of either APOL1-G0 or APOL1-G1 variants in the ApoE-KO mice." (PMID 39803526, 2024). "In early atherosclerosis, CD73 knockout promoted plaque area in apoE-/- mice at 12 weeks of age." (PMID 39735551, 2024). "Due to the absence of Apolipoprotein E (ApoE), these mice are prone to develop hypercholesterolemia and atherosclerosis." (PMID 38558816, 2024). "Conversely, studies in APOE*3-Leiden mice indicated that inulin did not reduce hypercholesterolemia or atherosclerosis development." (PMID 39449970, 2024). "The absence of apolipoprotein-E (ApoE) fosters hypercholesterolemia and spontaneous atherosclerosis in mice, mirroring the process observed in humans." (PMID 38570516, 2024). "This correlates with increased atherosclerotic plaque in an ApoE atherosclerosis mouse mutant lacking NRP1 expression in the endothelium, indicating a key anti-inflammatory and atheroprotective role of endothelial NRP1." (PMID 38323651, 2024). "To this aim, we have generated double-knockout mice lacking ASGR1 (ASGR1−/−) and ApoE−/− and characterized the development of atherosclerosis." (PMID 39616371, 2024). "APOE in the peripheral circulation can regulate brain function either by directly affecting the endothelial cells of the BBB or by indirectly influencing endothelial and neuronal functions through lipid metabolism, atherosclerosis, and peripheral inflammation." (PMID 39273520, 2024). "The amount of Tregs was reduced in mice that developed atherosclerosis compared to ApoE-/- mice in which no atherosclerotic plaques were detected." (PMID 39399488, 2024). "Associations of VIM quintile with TC, HDL-C, non-HDL-C, and LDL-C trajectory groups, APOE-ε4 genotype, history of malignant neoplasm, atherosclerosis, age, or alcohol use also did not retain significance after Bonferroni adjustment in the MCI cohort." (PMID 39586400, 2024). "Concerning the topography of lesions, the different anatomical sites at which APOE*3-Leiden.CETP mice develop atherosclerosis have, to our knowledge, not been formally mapped." (PMID 38428154, 2024). "Our study found that reducing non-HDLc while maintaining HDLc levels in the ApoE + Cap group was critical for delaying atherosclerosis progression in the aorta and reducing advanced lesions in the carotid artery." (PMID 39339767, 2024). "We observed that T0901317 treatment not only failed to reduce atherosclerosis burden, but actually stimulated the development of atherosclerotic lesions in chow-diet-fed hypercholesterolemic APOE knockout mice." (PMID 38672446, 2024). "Furthermore, in vivo experiment showed that, the atherosclerosis and ferroptosis protective effects of MCL were eliminated in ApoE−/− mice with KEAP1-R483S injection." (PMID 38100883, 2024). "Clearly, inulin showed beneficial effects in alleviating atherosclerosis in the ApoE−/− mice fed a HFD model rather than in the E3L mice." (PMID 39449970, 2024). "Recent studies have found that deletion of CCR7 not only leads to reduced plaque content in mice, but also results in disturbed access of T cells to and from the site of plaque inflammation.The ApoE-/- mice lacking CD4+ T cells show reduced atherosclerosis." (PMID 39399488, 2024).
atherosclerosis (continued). "Loss of GIPR induced aortic atherosclerosis and inflammation in ApoE−/−:Gipr−/− high fat diet-fed mice despite a reduced weight gain and preserved glucose homeostasis compared to ApoE−/−:Gipr+/+ mice, further confirming the anti- inflammatory role of GIP in atherosclerosis." (PMID 39834741, 2024). "In the present study, we explored the effects of ADF on the progression of atherosclerosis in atherogenic mice lacking apolipoprotein E (Apoe−/−)." (PMID 39872376, 2024). "It signals via the Ccr6 receptor and the importance of the CCL20/Ccr6 axis for development of atherosclerosis was demonstrated in ApoE−/− mice lacking Ccr6, which had reduced size of the atherosclerotic lesions." (PMID 38350853, 2024). "Another showed also in ApoE-/- mice that NaF PET/CT imaging is suitable for monitoring atherosclerosis development without or with only spotty CT-calcification." (PMID 36826950, 2023). "For instance, an animal study found that a high-iron diet attenuates atherosclerosis in mice lacking apolipoprotein E." (PMID 37275636, 2023). "Our previous study demonstrated a beneficial effect of low (0.1 mmol/kg/day) and moderate (1 mmol/kg/day) dose nitrate in preventing the development of atherosclerosis in the apoE−/− mouse, with no additional benefit observed with the high dose nitrate." (PMID 36853380, 2023). "A study has also found that LPS can increase NK cells and NKT cells in ApoE -/- mice but not in ApoE -/- CD1d -/- mice; meanwhile, the atherosclerosis area in mice is not significantly increased." (PMID 37163428, 2023). "In APOE*3-Leiden.CETP mice (atherosclerosis model) inulin did not reduce hypercholesterolemia or atherosclerosis development and even resulted in manifestations of hepatic inflammation when combined with a high percentage of dietary cholesterol." (PMID 36678325, 2023). "Res.; and 3) interaction and synergies of Ang II and HFD in ApoE-KO background contribute significantly to pathological differences between abdominal versus thoracic aorta in developing different aortic diseases, including AAA and atherosclerosis." (PMID 37731512, 2023). "To test this hypothesis, we examined the burden and severity of atherosclerosis using Arf6 heterozygous (HET) and wildtype (WT) littermate control mice on the apolipoprotein E knockout (ApoE-/-) background." (PMID 37163513, 2023). "Plasma interleukin-35 (IL-35) is increased in ApoE-/- mice and patients with hypercholesterolemia, and IL-35 suppresses mitochondrial ROS-induced H3K14 acetylation, which inhibits endothelial activation and alleviates the development of atherosclerosis." (PMID 37244925, 2023). "Capsaicin administration was described to ameliorate vascular smooth muscle foam cell formation and to attenuate atherosclerosis in ApoE knockout mice on a high-fat diet, but not in ApoE/TRPV1 double-knockout counterparts." (PMID 36787302, 2023). "Double knockout mice (ApoE and Gal-3) with standard diet did not develop atherosclerosis in the long term, as opposed to ApoE knockout expressing Gal-3." (PMID 38170009, 2023). "al., demonstrated that platelet-derived growth factor β (PDGF-β) promotes smooth muscle proliferation resulting in atheroprogression and inhibition of PDGF-β suppressed atherosclerosis in ApoE-/- mice without altering plasma lipids." (PMID 37163513, 2023).
atherosclerosis (continued). "Iron chelators or dietary iron restriction slowed atherosclerosis development in ApoE(−/−) mice without influencing serum total cholesterol or triglyceride levels." (PMID 37791060, 2023). "In conclusion, adropin can reduce atherosclerosis in ApoE-/-/Enho-/- mice through non-lipid-regulating pathway, by inhibiting EndMT via the TGF-β/Smad2/3 signaling pathway." (PMID 37903785, 2023). "Curcumin has also been shown to protect against atherosclerosis in mice lacking apolipoprotein E by inhibiting Toll-like receptor 4 expression, in addition to its ability to suppress cholesterol accumulation in macrophage foam cells and atherosclerosis." (PMID 37241765, 2023). "Despite the importance of blood lipid in atherosclerosis, we found that adropin imposed no impact on the blood lipid and body weight in the ApoE-/- mice." (PMID 37903785, 2023). "It had been verified in ApoE (−/−) mice that the over expression of DCN could reduce inflammation in atherosclerotic plaques, thereby decelerating the progression of atherosclerosis." (PMID 37089432, 2023). "Moreover, local application of MI-2 significantly reduced carotid neointima lesions and atherosclerosis in C57BL/6J mice and apolipoprotein-E knockout (ApoE−/−) mice, respectively, which were both ameliorated by co-treatment with Fer-1." (PMID 38097554, 2023). "We here conclude that in hyperlipidemic ApoE−/− mice, B cell specific TNIK deficiency does not affect atherosclerosis." (PMID 37215541, 2023). "In the absence of ApoE, mice exhibit severe hyperlipidemia, develop spontaneous atherosclerotic lesions, and have become a widely utilized animal model for studying atherosclerosis." (PMID 38062308, 2023). "Astaxanthin also suppressed foam cell formation and atherosclerosis development by enhancing ABCA1, ABCG1, and SR-B1 expression in apoE-/- mice 133, 134, suggesting that circUGGT2 may be an anti-atherosclerotic RNA in vivo." (PMID 37324939, 2023). "The whole genome was hypomethylation in peripheral blood mononuclear and aortas of 4-week-old ApoE-null mice, a classic atherosclerotic animal model, in which stage that none of histological signs of atherosclerosis appears." (PMID 36875456, 2023). "We found that chronic exposure to constant lighting conditions, which caused severe circadian disruption, increased atherosclerosis and VLDL/LDL-cholesterol concentrations in male, but not female, ApoE−/− mice fed low-fat diet." (PMID 37064902, 2023). "In the absence of APOE, mice develop severe atherosclerosis due to the accumulation of remnant lipoproteins, thereby underlining the crucial role of APOE in lipoprotein metabolism and CVD." (PMID 37796905, 2023). "explored the pathogenesis of atherosclerosis from the perspective of macrophage polarization and energy metabolism and found that HDGF was highly expressed in the aortas of patients with atherosclerosis and APOE knockout mice, as well as in M1 macrophages." (PMID 37671161, 2023). "Moreover, our findings indicate that STING agonists exacerbate atherosclerosis, vascular inflammation, and ox-LDL-induced endothelial cell inflammation in ApoE−/− mice." (PMID 37761020, 2023). "In atherosclerosis mice lacking ApoE, the administration of H2S donor, NaHS or GYY4137, resulted in decreased area of atherosclerotic plaque, infiltration of macrophages, inflammation in the aorta, and levels of lipids in the bloodstream." (PMID 38074127, 2023). "For atherosclerosis, local delivery of IL-2 to atherosclerotic lesions or treatment with anti-CD3 and IL-2/anti-IL-2 mAb complexes led to a reduction in atherosclerosis due to Treg expansion in ApoE-/- mice." (PMID 36761778, 2023).
atherosclerosis (continued). "Importantly, in our study, we found that the expression of SFRP4 was elevated in ApoE KO mice, indicating that SFRP4 play a role in the progression of atherosclerosis." (PMID 37143778, 2023). "Blocking or inhibiting IL-17 in mice lacking the ApoE gene was found to promote the development of atherosclerosis." (PMID 38004268, 2023). "In ApoE-/- mice, overexpression of IGFBP1 reduced atherosclerosis." (PMID 38157252, 2023). "Early research showed that the lack of ApoE resulted in hyperlipidemia and atherosclerosis-like cardiovascular diseases in people and animals." (PMID 37091976, 2023). "Furthermore, to investigated if E2 signaling regulates lipid metabolism and is protective against the early stages of atherosclerosis, lipid metabolism and arterial plaques were also evaluated in a foam-cell model and in ovariectomized (OVX) ApoE–/– mice." (PMID 35865386, 2022). "ApoE-⁄--knockout animals that received a cholesterol-enriched diet showed a correlation between a lack of ApoE and increased fat intake, thus promoting the development of atherosclerosis." (PMID 35269673, 2022). "The resulting effect of these differences is the ability of apoE to suppress the remodeling of the extracellular matrix during atherosclerosis without the adverse effect on normal vascular architecture under normal conditions." (PMID 36077289, 2022). "In order to assess the effects of systemic exposure to JAK2 inhibitors on atherosclerosis, we fed ApoE-null mice with HCD with or without ruxolitinib for 16 weeks, starting at 6 weeks of age, and assessed for atherosclerotic burden." (PMID 35169231, 2022). "To determine whether macrophage inflammation is involved in Hcy-related atherosclerosis, we detected F4/80 (a positive marker of macrophages) and proinflammatory cytokines (IL-1β, IL-6, and TNF-α) in the aortic root of ApoE−/− mice." (PMID 34725437, 2022). "This was dependent on S1P signaling through S1PR3 and resulted in dramatically enhanced atherosclerosis in ApoE−/−/S1PR3−/− mice, where DOP treatment had no additional effect." (PMID 36077004, 2022). "Dietary supplementation of choline in apolipoprotein E deficient mice (ApoEˉ/ˉ) increases TMAO levels and as such atherosclerosis, while no enhancement in the plasma TMAO level was observed in germ-free (GF) ApoEˉ/ˉ." (PMID 36556351, 2022). "To determine whether VCAM1+ SMCs were involved in atherosclerosis, we examined the presence of VCAM1+ SMCs in ApoE–/– mice fed with Western diets." (PMID 36278486, 2022). "We developed our model on the basis of data from APOE -/- mice which develop atherosclerosis without interventions." (PMID 35921269, 2022). "For example, in hypercholesterolemic apolipoprotein E knockout (ApoE-KO) mice, atherosclerosis development accelerates without a proper functioning eNOS, further suggesting that eNOS has a protective role on the CVS." (PMID 35072089, 2022). "E2 and statin co-treatment significantly decreased lipid accumulation in vitro, after HFD consumption for 12 weeks, administration of E2 and a statin together significantly relieved blood-lipid disorders and hindered progression of atherosclerosis and fatty-liver damage in OVX ApoE–/– mice." (PMID 35865386, 2022).
atherosclerosis (continued). "In 14-week-old female ApoE−/− mice administered varying doses of intraperitoneal heat-killed BCG, mice receiving the highest dose of 1 mg heat killed BCG also developed advanced, calcified atherosclerosis." (PMID 36290415, 2022). "In this study, we crossed the ApoE knockout (ApoE-KO; ApoE−/−) atherosclerotic mouse model with the NOS3 knockout (NOS3-KO; NOS3−/−) hypertensive mouse model to establish an ApoE/NOS3 double knockout (ApoE/NOS3-KO; ApoE/NOS3−/−) hypertensive atherosclerosis mouse model." (PMID 36360235, 2022). "VE-cadherin regulation, aortic remodeling and atherosclerosis were studied in IH-exposed C57Bl/6J or ApoE-/-mice treated or not with Src-tyr-kinases inhibitors (Saracatinib/Pazopanib) or a HIF-1 inhibitor (Acriflavine)." (PMID 35806017, 2022). "The preventive treatment with lycopene would have added little to the study, considering that ApoE mice represent a model of genetic atherosclerosis and develop plaques regardless of the HFD, which serves as an accelerator of the disease." (PMID 35883529, 2022). "To better explore the potential mechanism of gut microbiota in the improvement of atherosclerosis by capsaicin, we further investigated the cecal metabolites in ApoE−/− mice using non-targeted metabolomics analysis." (PMID 36297020, 2022). "In ApoE-/- mice, atherosclerosis was reduced without T-bet, IFN-γ (Th1 cells characteristic cytokine), or IFN-γ receptors." (PMID 36685487, 2022). "These VLDLs and their remnant particles enriched in apolipoprotein E and apolipoprotein C-III (apoC-III) may retain in the arterial wall, contributing to the initiation and progression of atherosclerosis, vascular inflammation, and prothrombotic effects." (PMID 36675730, 2022). "In a mouse model of atherosclerosis, nilotinib promoted aortic wall atherosclerosis in ApoE-/- mice, whereas imatinib showed no proatherogenic effect." (PMID 36009482, 2022). "Initial studies in NLRP3/ApoE, ASC/ApoE and caspase-1/ApoE double knockout mouse models failed to reveal significant effects on atherosclerosis, plaque macrophage numbers or stability." (PMID 36459456, 2022). "Moreover, E2 and statin co-treatment significantly reduced lipid accumulation in vitro and hindered the progression of atherosclerosis and fatty-liver damage in OVX ApoE–/– mice." (PMID 35865386, 2022). "The treatment with DFO was demonstrated to attenuate atherosclerosis with a significant reduction in ferritin in the serum, iron, FTL and FTH mRNAs and proteins in the aortic tissues in ApoE–/– mice." (PMID 35669479, 2022). "Here we investigated the role of NF-κB signalling in SMCs in atherosclerosis by generating and analysing ApoE−/− mice lacking NEMO specifically in SMCs." (PMID 35869246, 2022). "Studies have also reported that diabetic APOE–/– mice can increase the NOX1 level by mediating the overexpression of ET-1, increasing the production of ROS in peri-aortic adipose tissue, and promoting atherosclerosis progression." (PMID 36407440, 2022). "The ApoE knockout mice were genetically modified to C57BL/6-Apoeem1Narl/Narl mice by using CRISPR/Cas9, and their phenotypes were manipulated with a high- cholesterol and high-fat WD to induce pathological atherosclerosis." (PMID 35256637, 2022). "In addition, BAG3 overexpression reduced atherosclerotic lesions in ApoE−/− mice, indicating that BAG3 plays an important protective role in atherosclerosis." (PMID 35893075, 2022). "Diabetic ApoE−/− mice exhibited more advanced atherosclerosis than a nondiabetic ApoE−/− group of the same age." (PMID 35205155, 2022). "However, the severity of intracranial atherosclerosis in both WHHL and apoE KO rabbits was lower than that of extracranial atherosclerosis in the same animals." (PMID 35712258, 2022).